CELSR1 (cadherin EGF LAG seven-pass G-type receptor 1)
Description:
Receptor that may have an important role in cell/cell signaling during nervous system formation.
Synonyms: hFmi2; CDHF9; FMI2; ME2; ADGRC1; LMPHM9; YNS
Tractability: Antibody: its Gene Ontology location is reachable by antibodies, with high confidence; UniProt places it where antibodies can reach, with medium confidence; UniProt predicts a signal peptide or a membrane-spanning region; the Human Protein Atlas places it where antibodies can reach. PROTAC: ubiquitination databases record sites on it.
Gene: Protein-coding gene on chromosome 22 (46,360,834 to 46,537,620, reverse strand). Ensembl gene ENSG00000075275.
Subcellular location: Cell membrane
Subcellular location (Human Protein Atlas): Plasma membrane; Nucleoplasm
Gene Ontology:
Molecular function: calcium ion binding; G protein-coupled receptor activity; transmembrane signaling receptor activity
Biological process: apical protein localization; axonogenesis; cell-cell adhesion mediated by cadherin; central nervous system development; establishment of body hair planar orientation; establishment of planar polarity; establishment of planar polarity of embryonic epithelium; lateral sprouting involved in lung morphogenesis; neural tube closure; neuron migration; orthogonal dichotomous subdivision of terminal units involved in lung branching morphogenesis; planar dichotomous subdivision of terminal units involved in lung branching morphogenesis; protein localization involved in establishment of planar polarity; regulation of actin cytoskeleton organization; Rho protein signal transduction; Wnt signaling pathway, planar cell polarity pathway; cell adhesion; cell surface receptor signaling pathway; G protein-coupled receptor signaling pathway; homophilic cell-cell adhesion; nervous system development
Cellular component: plasma membrane; adherens junction; membrane
Genetic constraint (gnomAD): Loss-of-function variants: 110 observed, 228.37 expected, observed/expected ratio (o/e) 0.48, 90% interval 0.41 to 0.56. The upper end of that interval is the gene's LOEUF score, 0.56, which puts it in group 2 of 6, group 1 being the genes least tolerant of losing a copy. Missense variants: 4,102 observed, 4,214.2 expected, observed/expected ratio (o/e) 0.97, 90% interval 0.95 to 1. Synonymous variants: 2,110 observed, 1,850.6 expected, observed/expected ratio (o/e) 1.14, 90% interval 1.1 to 1.18.
Homologues: Orthologues: chimpanzee CELSR1 (94% identical), mouse Celsr1 (81% identical), rat Celsr1 (81% identical), dog CELSR1 (81% identical), pig CELSR1 (80% identical), guinea pig CELSR1 (76% identical), tropical clawed frog celsr1 (65% identical), zebrafish celsr1a (60% identical), macaque CELSR1 (58% identical), zebrafish celsr1b (58% identical), Drosophila melanogaster stan (37% identical), Caenorhabditis elegans fmi-1 (25% identical), and 2 more. Paralogues in human: CELSR2 (55% identical), CELSR3 (48% identical), FAT1 (21% identical), FAT3 (20% identical), FAT4 (18% identical), FAT2 (17% identical).
Diseases named in the same sentence as CELSR1 in open-access papers:
CELSR1 is named in the same sentence as 70 diseases in open-access papers, as found by Europe PMC text mining. Sharing a sentence is not in itself a finding about the gene and the disease. The quoted sentences say what the papers report.
spina bifida (11 papers, 2013 to 2025). A congenital neural tube defect in which vertebrae are not fully formed. "It has been shown in the literature that mutations in Cadherin EGF LAG Seven‐Pass G‐Type Receptor 1 (CELSR1) contribute to increased risk of spina bifida." (PMID 40666233, 2025). "CELSR1 is a planar cell polarity gene in which mutations are known to cause neural tube defects including spina bifida." (PMID 31190668, 2019). "Unique sequence variants in both VANGL2 and CELSR1 have been previously identified in human spina bifida patients, but to the authors’ knowledge skeletal structure has not been investigated in these patients." (PMID 29463853, 2018). "Lei and colleagues detected deleterious CELSR1 variants in about 3% of spina bifida cases collected in the U.S. cohort." (PMID 29618362, 2018). "The renal tract malformations that we documented in 5 of 13 babies with spina bifida carrying CELSR1 variants represent true developmental defects because they were detected in the fetal or immediate postnatal periods." (PMID 27597235, 2016). "In contrast, in our cohort of 13 individuals with spina bifida and CELSR1 variants, we recorded 1 case of unilateral renal agenesis, a significant difference (P = 0.001, Fisher exact test) versus the control population." (PMID 27597235, 2016). "Our findings suggest that CELSR1 mutations contribute to the risk of spina bifida in a cohort of spina bifida patients from California." (PMID 24632739, 2014). "Combined with the SNVs, about 3% (6 in 192) of the spina bifida patients in our cohort possess CELSR1 deleterious or predicted-to-be-deleterious variants." (PMID 24632739, 2014). "In summary, our study on a California spina bifida cohort indicates that mutations in CELSR1 contribute to the development of spina bifida." (PMID 24632739, 2014). "In this study, we sequenced all exons of CELSR1 in 192 spina bifida patients from a California population to determine the contribution of CELSR1 mutations in the studied population." (PMID 24632739, 2014). "In total, 3% of our spina bifida patients carry deleterious or predicted to be deleterious CELSR1 mutations." (PMID 24632739, 2014). "In addition to CELSR1, other key genes in this pathway have been associated with increased spina bifida risk." (PMID 40666233, 2025). "Interestingly, we demonstrated patients with CELSR1 mutations and spina bifida can have significant renal malformations." (PMID 27597235, 2016). "Furthermore, heterozygous CELSR1 variants have been reported in humans with spina bifida." (PMID 27597235, 2016). "Finally, we asked whether humans born with spina bifida and CELSR1 mutations might have renal tract malformations." (PMID 27597235, 2016). "Previous studies reported that the damaging mutations of CELSR1 are associated with diverse NTD phenotypes in humans, such as craniorachischisis and spina bifida." (PMID 29618362, 2018). "Only spina bifida is found in digenic heterozygotes at Vangl2;Ptk7, Vangl2;Grhl3, Vangl2;Sec24b, and Celsr1;Ptk7." (PMID 30134561, 2018). "However, the contribution of CELSR1 mutations in the etiology of spina bifida is still unknown." (PMID 24632739, 2014). "In this study, we investigated the CELSR1 coding region sequence among a cohort of spina bifida infants born in California by Sanger sequencing." (PMID 24632739, 2014). "Analysis of planar cell polarity genes in humans has revealed mutations in SCRIB and CELSR1 in craniorachischisis cases, while mutations in VANGL1, VANGL2, CELSR1, and FZD6 have also been identified in spina bifida and anencephaly cases." (PMID 23733478, 2013). "Genetic factors including variations in some specific genes such as MTHFR, MTHFD1, MTRR, VANGL1, VANGL2, CELSR1, and FUZ, as well as variants in the T-locus on chromosome 6q have also been studied in the development of spina bifida and other spinal dysmorphisms." (PMID 39835283, 2025).
spina bifida (continued). "Discovery of heterozygous digenic deleterious variants in human NTD cases with spina bifida (i.e. PTK7/ SCRIB) and anencephaly (i.e. CELSR1/SCRIB; CELSR1/DVL3) strongly support the strategy of screening PCP genes to discover risk alleles contributing to human NTDs3,12." (PMID 33574475, 2021). "Finally, different individuals can have craniorachischisis or exencephaly or spina bifida in digenics heterozygous at Vangl2;Scrib or Celsr1;Scrib." (PMID 30134561, 2018). "Case NTD_15 with LRP6 p.Arg386Cys and CELSR1 p.Arg714His had both anencephaly and spina bifida." (PMID 29618362, 2018). "At the least, our current results should encourage further studies to determine whether spina bifida and PCP mutations (including CELSR1 and VANGL2) coexist with kidney malformations." (PMID 27597235, 2016). "We also screened for other PCP genes including CELSR1, SCRIB, and LRP6 in the 192 US spina bifida, but no double PCP damaging missense variants were found in our current analysis." (PMID 30689296, 2019). "Our study identified novel CELSR1 TG indels and SNV's in spina bifida patients." (PMID 24632739, 2014). "It was demonstrated in mice that homozygous PCP mutations caused craniochisichisis, as shown for Vangl2, Celsr1, and Ptk7 while double heterozygosity for a PCP mutation and non-PCP mutation can cause spina bifida, as shown for Vangl2/Dact1 double heterozygotes." (PMID 24632739, 2014).
craniorachischisis (8 papers, 2013 to 2021). Craniorachischisis is the most severe form of neural tube defect in which both the brain and spinal cord remain open to varying degrees. "Robinson and co-workers detected missense variants in CELSR1 increased risk of craniorachischisis in humans." (PMID 29618362, 2018). "Perhaps the CELSR1 TG indels combined with other non-PCP mutations caused the myelomeningoceles that we observed, and that in the Robinson's study, the moderate CELSR1 mutations combined with other functional PCP mutations resulted in craniorachischisis." (PMID 24632739, 2014). "In contrast, the study by Robinson and co-workers found SNV's that moderately altered the biological function of the CELSR1 protein, yet the associated defect was craniorachischisis, a more severe type of NTD." (PMID 24632739, 2014). "For example, homozygous core PCP pathway mutations like Vangl2 or Celsr1 usually result in the severe neural tube defect, craniorachischisis, whereas the Atmin homozygotes show exencephaly, a different neural tube closure defect." (PMID 24852369, 2014). "Three out of five human fetuses with craniorachischisis were found to have two rare variants of CELSR1 and three individuals with lipomyelomeningocele or spinal lipoma each had two rare variants of CELSR1." (PMID 25128525, 2014). "In humans, functional CELSR1 single nucletotide variants (SNVs) have been identified in fetuses with craniorachischisis, and predicted-to-be-deleterious CELSR1 SNVs have been detected in a few cases with NTDs or caudal agenesis." (PMID 24632739, 2014). "A cross between ScribCrc/+ and a second Celsr1 mutant allele, spin-cycle also generated doubly heterozygous fetuses with isolated craniorachischisis (n=10/18), or craniorachischisis with abdominal wall defect (n=1/18), as well as eyelid closure defects (n=2/2)." (PMID 25128525, 2014). "In yet another type of digenic cause, high frequencies of craniorachischisis are found in mutants that are double heterozygotes for mutations at two PCP genes of different gene families (e.g., Vangl2;Celsr1, Vangl2;Dvl2, Vangl2;Scrib, or Celsr1;Scrib)." (PMID 30134561, 2018). "Loss of function (LoF) alleles of the core components of the PCP pathway, including Celsr1 and Vangl2 produces craniorachischisis in mice." (PMID 29618362, 2018). "Among craniorachischisis cases, about 20% have potentially deleterious variants in single PCP genes (VANGL2, CELSR1, SCRIB or DACT1)." (PMID 30134561, 2018). "Vangl2, Scrib and Celsr1 are among the most intensively studied mouse PCP genes, each of which causes craniorachischisis in homozygous mutants." (PMID 25128525, 2014). "Several of the mouse mutants with craniorachischisis have mutations that disrupt core components of the PCP pathway, including Celsr1, Vangl1, Vangl2, Fzd3, Fzd6, Dvl1, Dvl2 and Dvl3." (PMID 25128525, 2014). "In mice, mutations in Vangl2, Celsr1, Dishevelled and Frizzled result in the NTD known as craniorachischisis." (PMID 24632739, 2014). "In mice, Celsr1 mutants exhibited craniorachischisis, the most severe form of NTDs." (PMID 24632739, 2014). "In some examples, mutants are homozygous at only one PCP gene (e.g., Vangl2, Celsr1, Scrib or Sec24b) and all embryos have craniorachischisis; heterozygotes do not." (PMID 30134561, 2018). "We conclude that craniorachischisis originates through failure of Closure 1 in homozygotes for all three PCP mutants, but that ScribCrc/+ embryos do not exhibit delayed closure, unlike Celsr1 or Vangl2 heterozygotes." (PMID 25128525, 2014).
lymphedema (6 papers, 2016 to 2025). Excess fluid collection in tissues, causing swelling. "For instance, TFC20 has been associated with intellectual disability and ASD, and CELSR1 has been linked to lymphedema." (PMID 40429797, 2025). "The case also provides additional proof of the pathogenic effect of CELSR1 on hereditary lymphedema." (PMID 34128868, 2021). "In our patient, CELSR1 completely included in the deletion was identified as the potential cause of the primary lymphedema and PLE." (PMID 34128868, 2021). "In addition, CELSR1-deficient mouse has found to have microcephaly and cortical hypoplasia, but also with defects in neural tube and caudal agenesis, lymphedema, or several kidney disorders." (PMID 40429797, 2025). "This study refines genotype–phenotype correlations for seizures, renal anomalies, and lymphedema, particularly in relation to deletions involving CELSR1 and GRAMD4." (PMID 40429797, 2025). "We reanalyzed the data in Samogy-Costa paper and found that of 34 patients with 22q13.3 deletion syndrome, 15 (44.1%, 15/34) carry the deletion of CELSR1, while only 4 of them (4/15, 26.7%) reported lymphedema." (PMID 34128868, 2021). "Additionally, renal abnormalities and lymphedema were significantly more prevalent among patients with deletions encompassing the CELSR1 and GRAMD4 genes (χ2 = 18.734; degrees of freedom = 2; p < 0.001)." (PMID 40429797, 2025). "Lymphedema was present in four individuals (23%), all harboring CNVs encompassing the CELSR1 gene." (PMID 40102980, 2025). "Interestingly, several genes within Region 2, including CERK, TBC1D22A, CELSR1, and GRAMD4 were found to be implicated in seizures, renal abnormalities, lymphedema, macrocephaly, and developmental delay in PMS." (PMID 40429797, 2025). "Among the 27 primary lymphedema patients included in this study, the family of only one patient was genetically confirmed to have a likely pathogenic variant of CELSR1, which has been previously reported as causative for nonsyndromic hereditary lymphedema." (PMID 35948757, 2022). "However, male patients with CELSR1 deletion and lymphoedema were recorded in Samogy-Costa study, which conflicts with the sex-limited penetrance." (PMID 34128868, 2021).
anencephaly (3 papers, 2013 to 2021). A rare neural tube defect during pregnancy, resulting in the absence of a large portion of the brain and skull in the fetus. "This study highlights the potential involvement of PCP genes including CELSR1 in association with anencephaly phenotypes, and also PDGFRA as strong NTD candidates in humans." (PMID 29205322, 2018). "Five anencephaly cases carried rare or novel CELSR1 missense variants, three of whom carried additional rare potentially damaging PCP variants: 01F377 (CELSR1 c.6362G>A and PRICKLE4 c.730C>G), 2F07 (CELSR1 c.8807C>T and DVL3 c.1622C>T), 618F05 (CELSR1 c.8282C>T and SCRIB c.3979G>A)." (PMID 29205322, 2018).
ischemic stroke (3 papers, 2011 to 2023). A stroke disorder caused by obstruction of blood flow to the brain, due to thrombotic (local blood clot formation) or embolic (due to a blood clot or other material traveling from another site) event. "Celsr1 was identified as a susceptibility gene for ischemic stroke in Japanese individuals by a genome-wide association study." (PMID 32070035, 2020). "Another gene CELSR1 (located at 22q11–13) is associated with ischemic stroke in recent Japanese GWAS." (PMID 21698157, 2011). "Although Celsr1 has been identified as a susceptibility gene for ischemic stroke, the role of CELSR1 in cerebral ischemia injury is unknown." (PMID 32070035, 2020). "Although Celsr1 has been reported to be a sensitive gene for stroke, the effect of CELSR1 in ischemic stroke is still not known." (PMID 32070035, 2020).
microcephaly (3 papers, 2021 to 2025). A congenital or acquired developmental disorder in which the circumference of the head is smaller than normal for the person's age and sex. "Of the IP-enriched PCP genes, mice lacking Celsr1 have microcephaly, due to reduced numbers of IPs and PNs." (PMID 34321999, 2021).
ovarian carcinoma (3 papers, 2020 to 2024). A malignant neoplasm originating from the surface ovarian epithelium. "Recently, CELSR1 upregulation has also been linked to poor ovarian cancer prognosis, likely by promoting proliferation, migration, and invasion." (PMID 39854621, 2024). "CELSR1 was shown to promote progression and paclitaxel resistance of ovarian cancer in vitro and in vivo." (PMID 33428592, 2021).
primary lymphedema (3 papers, 2021 to 2024). A congenital condition that results in swelling in the arms or legs, and can occur during adolescence or adulthood. "We also report the possibility that a variant in CELSR1, which to the best of our knowledge has not been reported earlier in this population, is a cause of nonsyndromic primary lymphedema in Koreans and East Asians." (PMID 35948757, 2022).
deafness (2 papers, 2023). An inherited or acquired condition characterized by the complete loss of the ability to hear from one or both ears. "There were 18 genes linked only to Metabolic hearing loss (including four deafness genes: DMD, DUOX2, CELSR1 and ELMO3) and 54 genes linked only to Sensory hearing loss (including four deafness genes: ARHGAP21, LMO7, UBE3B and ADGRV1)." (PMID 38011198, 2023). "PKHD1L1, DUOX2, CELSR1, ELMO3, ARHGAP21, LMO7 and UBE3B are all defined as deafness genes through work on the mouse orthologues." (PMID 37163093, 2023).
hypoplastic left heart syndrome (2 papers, 2023 to 2024). Hypoplastic left heart syndrome (HLHS) refers to the abnormal development of the left-sided cardiac structures, resulting in obstruction to blood flow from the left ventricular outflow tract. "CELSR1, a cadherin superfamily member, is mutated in families with BAV and hypoplastic left heart syndrome." (PMID 37961530, 2023).
Infertility (2 papers, 2024). "It was reported that the defect of CELSR1 resulted in ectopically-branched folds in mice and even infertility in humans and mice." (PMID 37729465, 2024).
lung adenocarcinoma (2 papers, 2020 to 2023). A carcinoma that arises from the lung and is characterized by the presence of malignant glandular epithelial cells. "Promotes EC tumor cell invasion by targeting PPWD1 and increases EC permeability via suppressing CELSR1 in lung adenocarcinoma." (PMID 33363174, 2020).
lymphatic malformation 9 (2 papers, 2022 to 2023). "In particular, heterozygous loss-of-function mutations in CELSR1 are correlated with Lymphatic malformation 9 (OMIM: 619319), while homozygous mutations in FAT4 are correlated with Hennekam lymphangiectasia-lymphedema syndrome 2 (OMIM: 616006)." (PMID 35806420, 2022).
Macrocephaly (2 papers, 2023 to 2025). Occipitofrontal (head) circumference greater than 97th centile compared to appropriate, age matched, sex-matched normal standards. "A genomic region on 22q13.31 was found to be significantly associated with macrocephaly with CELSR1, GRAMD4, and TBCD122 suggested as candidate genes." (PMID 36980813, 2023). "There are three genes that are proposed as the main candidates for macrocephaly (TBC1D22A, CELSR1, and GRAMD4) given their location in the highly associated genomic regions, proposed function, or high probability of loss of function intolerance." (PMID 36980813, 2023). "Regarding some functionality of these genes (TBC1D22A, CELSR1, and GRAMD4), we propose previously a region of 4.5 to 8 Mb from the telomere, strongly associated with macrocephaly in PMS, also supported by this study, and aligned with other works, suggesting to GRAMD4 associated with macrocephaly." (PMID 40429797, 2025).